KLK12 (kallikrein related peptidase 12)
Diseases named in the same sentence as KLK12 in open-access papers:
KLK12 is named in the same sentence as 24 diseases in open-access papers, as found by Europe PMC text mining. Sharing a sentence is not in itself a finding about the gene and the disease. The quoted sentences say what the papers report.
breast carcinoma (6 papers, 2014 to 2025). "From microarray analyses, it turned out that KLK12 was the most strongly associated with low-grade malignancy in breast carcinomas among the 15 KLK members." (PMID 37176127, 2023). "In this study, KLK12 immunoreactivity was significantly associated with ER and PR status in breast carcinomas." (PMID 37176127, 2023). "In summary, we examined the gene expression profile of the KLK family in breast carcinomas by microarray analysis and newly identified that KLK12 was the most strongly associated with low-grade malignancy." (PMID 37176127, 2023). "KLK12 mRNA expression has been previously examined in breast carcinomas, but the association between KLK12 mRNA and the clinical outcome of breast cancer patients is still controversial." (PMID 37176127, 2023). "Therefore, in this study, we first studied the expression profile of 15 KLK genes in breast carcinomas by microarray data and newly identified that KLK12 was the most strongly associated with low-grade malignancy." (PMID 37176127, 2023). "KLK12 protease is a remarkable exception among the KLKs, since to date no protein expression has been reported for most cancer tissues, except for breast cancer." (PMID 41516101, 2025). "KLK12 expression was the most pronouncedly suppressed in the breast carcinomas with high-grade malignancy in this study." (PMID 37176127, 2023). "The role of KKL12 seems different among the tissues, and further examination will be warranted for a better understanding of the biological significance of KLK12 in breast cancer." (PMID 37176127, 2023). "Our present study demonstrated that KLK12 status was an independent favorable prognostic factor for both metastasis-free survival and breast cancer-specific survival of breast cancer patients." (PMID 37176127, 2023). "In this study, KLK12 immunoreactivity was detected in 51% of breast carcinomas, while it was positive in the epithelium of morphologically normal mammary glands." (PMID 37176127, 2023). "Univariate analysis for breast cancer-specific survival revealed lymph node metastasis, histological grade, pT, KLK12 status, and ER status as significant prognostic variables, in addition to Ki-67 status as a marginally significant variable." (PMID 37176127, 2023). "Prognostic analyses demonstrated that KLK12 was a favorable prognostic factor for both disease-free and breast cancer-specific survival of the patients." (PMID 37176127, 2023). "Following in vitro, experiments revealed that KLK12 knockdown increased cell proliferation and migration in breast cancer cells." (PMID 37176127, 2023). "Subsequently, we examined the effects of KLK12 on proliferation and migration in breast cancer cell lines." (PMID 37176127, 2023). "We transfected specific siRNA for KLK12 in MCF-7 and BT-474 breast cancer cells and performed the cell proliferation assay and migration assay to examine the effects of KLK12 on breast cancer progression." (PMID 37176127, 2023). "Applying SigFuge to a cohort of lung SQCC samples, we identified CDKN2A, a tumor suppressor gene known to be highly altered in lung SQCC, and KLK12, a gene recently shown to have differential isoform usage in breast cancer." (PMID 25030904, 2014). "However, recently, KLK12 was detected at significant concentrations in breast cancer tissue by immunostaining." (PMID 41516101, 2025). "Moreover, the multivariate analysis turned out that the KLK12 status was an independent favorable prognostic factor for both metastasis-free and breast cancer-specific survival of the patients." (PMID 37176127, 2023). "Next, we immunolocalized KLK12 in 140 breast carcinomas and evaluated its clinical significance." (PMID 37176127, 2023). "Furthermore, the knockdown of KLK12 significantly increased cell proliferation activity and cell migration of breast cancer cells." (PMID 37176127, 2023). "This is the first study that immunolocalized KLK12 in breast carcinomas." (PMID 37176127, 2023).
breast carcinoma (continued). "KLK12 was immunolocalized in the nucleus and cytoplasm of breast carcinoma cells." (PMID 37176127, 2023). "KLK12 was therefore considered to play a suppressive role in breast carcinomas." (PMID 37176127, 2023). "Two studies have examined expression of distinct KLK12 transcripts in breast cancer." (PMID 32028882, 2020). "Taken together, all data suggest that the protease KLK12 would play a pro-tumorigenic role in breast cancer whereas KLK12vs3 (encoding a truncated protein lacking a functional catalytic triad) would have a tumor suppressor role." (PMID 32028882, 2020). "In addition, KLK12 is reported to be an independent and favorable prognostic marker for breast cancer." (PMID 24510347, 2014). "Therefore, we subsequently performed immunohistochemistry for KLK12 in breast carcinoma tissues to clarify its clinicopathological significance, and in vitro studies were subsequently performed using breast cancer cells to prove the biological significance of KLK12 in breast cancers." (PMID 37176127, 2023). "The biological function of KLK12 has been unknown in breast cancers." (PMID 37176127, 2023). "Therefore, KLK12 may participate in the enzymatic cascade in breast carcinoma in cooperation with other KLK members." (PMID 37176127, 2023). "KLK12, KLK13, and KLK14 genes were downregulated in breast cancer, while KLK15 was overexpressed in more aggressive forms of prostate cancer." (PMID 33150763, 2020). "Subsequent immunohistochemical analysis demonstrated that KLK12 immunoreactivity was positive in the epithelium of non-neoplastic mammary glands, and it was positive in 51% of breast carcinomas." (PMID 37176127, 2023). "Since estrogen-mediated transactivation varies among the target genes, highly malignant breast carcinomas may more efficiently induce the genes promoting aggressiveness by estrogen rather than KLK12." (PMID 37176127, 2023). "Moreover, KLK12 protein has not been examined in breast cancers to the best of our knowledge." (PMID 37176127, 2023).
prostate carcinoma (6 papers, 2015 to 2024). A carcinoma that arises from epithelial cells of the prostate gland. "KLK6 and KLK12 are reported to be markers associated with highly aggressive prostate cancer, but future studies are still needed to validate these findings." (PMID 37240308, 2023). "Highly expressed genes defining the IDCP cluster, such as MUC6, MYO16, NPY, and KLK12, reflected the aggressive nature of high-grade prostate cancer." (PMID 38732035, 2024). "KLK12 was found reactivated in the PC3 prostate cancer cell line following treatment with 5-aza-2′-deoxycytidine (5-aza-dC)." (PMID 32028882, 2020). "These include KLK12 (log2FC 3.2 iCluster3) and HPN (log2FC 1.6–2.2), which have both been linked with prostate cancer aggressiveness." (PMID 26501111, 2015). "However, it should be borne in mind that KLK12 mRNA levels are upregulated in cancer tissues, including gastric, breast, and prostate cancer." (PMID 36293113, 2022).
gastric cancer (4 papers, 2010 to 2020). A primary or metastatic malignant neoplasm involving the stomach. "Blocking KLK12 expression in gastric cancer cells significantly inhibited proliferation by arresting cells in G0/G1 phase." (PMID 32028882, 2020). "Beside its implications in angiogenesis, KLK12 may also play a role in proliferation and migration of cancer cells, as described for gastric cancer cells in vitro." (PMID 32028882, 2020). "KLK12 expression in gastric cancer was found to be significantly and positively associated with higher tumor-node-metastasis (TNM) stage and patients with high KLK12 mRNA expression displayed a significantly poorer 5-year survival rate than those with low KLK12 expression." (PMID 32028882, 2020). "However, KLK12 was not able to modulate gastric cancer cell migration in the presence of basement membrane extracts containing mainly laminin and collagen IV, which are not cleaved by KLK12." (PMID 29679011, 2018).
lung carcinoma (3 papers, 2021 to 2024). "For instance, the lncRNA CASC15 promotes the proliferation and invasion of lung cancer cells via the miR-766-5p/KLK12 axis." (PMID 39588384, 2024). "- miR-766-5p act as tumor suppressor miRNA in lung cancer.- Ectopic expression of lncRNA CASC15 contribute to ling cancer progression by targeting miR-766-5p/KLK12 axis." (PMID 37205191, 2023). "Meanwhile, CASC15 can promote lung cancer metastasis via miR-766-5p/KLK12 axis." (PMID 34745939, 2021).
lung adenocarcinoma (2 papers, 2016 to 2018). A carcinoma that arises from the lung and is characterized by the presence of malignant glandular epithelial cells. "Lung adenocarcinoma and lung squamous cell carcinoma showed significant up-regulation of 3 KLKs: KLK6 (7-fold and 19-fold), KLK8 (3-fold and 15-fold) and KLK12 (2-fold and 3-fold) and significant down-regulation of KLK11 (6-fold and 5-fold)." (PMID 29707153, 2018).
triple-negative breast carcinoma (2 papers, 2020 to 2023). An invasive breast carcinoma which is negative for expression of estrogen receptor (ER), progesterone receptor (PR), and human epidermal growth factor receptor 2 (HER2). "In conclusion, our results revealed that positive KLK12 expression is remarkably associated with shortened DFS and OS, suggesting that KLK12 mRNA might be a prognostic biomarker and therapy target in triple-negative breast cancer." (PMID 32028882, 2020). "KLK12 mRNA expression levels were determined by qPCR in a homogenous cohort of 116 patients with triple-negative breast cancer." (PMID 32028882, 2020). "The present study focuses on the analysis of KLK12 mRNA expression in tumor tissue of triple-negative breast cancer (TNBC) patients." (PMID 32028882, 2020).
breast tumors (1 paper, 2020). "A similar observation was made for KLK12 in a recent study comparing breast tumor samples and matched non-tumor samples." (PMID 32028882, 2020). "A lack of KLK12 mRNA expression in a large proportion of the breast tumors examined (12/17) had already been noted by Yousef and collaborators (2000)." (PMID 32028882, 2020).
influenza infection (1 paper, 2022). "SPINK6‐specific inhibition of HAT, and its native target KLK5 and KLK12, as well as its upregulation upon infection, underscores the importance of SPINK6 in human influenza infection." (PMID 34826211, 2022).
lymph node metastasis (1 paper, 2023). "Immunohistochemical KLK12 status was positively associated with ER and PR status, while it was inversely associated with stage, pathological T factor, lymph node metastasis, and distant metastasis." (PMID 37176127, 2023). "The KLK12 status was positively associated with ER and PR status, while it was inversely associated with stage, pT, lymph node metastasis, and distant metastasis." (PMID 37176127, 2023). "According to the results of univariate analysis of distant disease-free survival using Cox, pT, lymph node metastasis, Ki-67 status, KLK12 status, histological grade, and ER status were significant prognostic factors." (PMID 37176127, 2023).
non-small cell lung carcinoma (1 paper, 2023). A group of at least three distinct histological types of lung cancer, including non-small cell squamous cell carcinoma, adenocarcinoma, and large cell carcinoma. "In a small number of HNCs, the MET (MET Proto-Oncogene, Receptor Tyrosine Kinase) gene transcript with missing exon 14, a form recognized as oncogenic in non-small cell lung cancer, and mRNAs of TP63 and KLK12 (Kallikrein Related Peptidase 12) genes as specific splicing variants have been reported." (PMID 38179168, 2023).
pulmonary TB (1 paper, 2022). "In addition, the clinical diagnostic value of KLK12 was also demonstrated in 20 healthy human controls (HCs) and 20 active pulmonary TB patients (pTB)." (PMID 36293113, 2022).
serous ovarian cancer (1 paper, 2020). "Similarly, no KLK12 mRNA expression was observed in tumor tissue samples from 32 patients with advanced high-grade serous ovarian cancer (own unpublished data)." (PMID 32028882, 2020).
systemic sclerosis (1 paper, 2018). A chronic disorder, possibly autoimmune, marked by excessive production of collagen which results in hardening and thickening of body tissues. "Inversely, KLK12 expression is downregulated in ECs from patients with systemic sclerosis, which is associated with abnormal angiogenesis." (PMID 29679011, 2018).
tuberculosis (1 paper, 2022). A chronic, recurrent infection caused by the bacterium Mycobacterium tuberculosis. "Herein, we sought to clarify the regulatory mechanism of KLK12 and its application in tuberculosis diagnosis." (PMID 36293113, 2022). "Importantly, KLK12 also has enormous potential for the clinical diagnosis of human tuberculosis (TB)." (PMID 36293113, 2022).
uterine corpus endometrial carcinoma (1 paper, 2018). A endometrial carcinoma (disease) that involves the body of uterus. "Furthermore, uterine corpus endometrial carcinoma displayed significant overexpression of KLK12 (3-fold) and downregulation of KLK1 (5-fold), KLK2 (4-fold) and KLK4 (6-fold)." (PMID 29707153, 2018).
tumor (10 papers, 2014 to 2024). "Positive KLK12 expression is remarkably associated with shortened DFS and OS, suggesting that KLK12 plays a tumor-supporting role in TNBC." (PMID 32028882, 2020). "Of the top 6 genes with higher degrees in tumour network compared to germline, expression of KLK12 is known to be a diagnostic and prognostic marker of gastric cancer." (PMID 27412732, 2016). "Among the co-expressed genes shared by DEFA5 and DEFA6, KLK12, which is responsible for tumor formation, was highly expressed in CRC." (PMID 36703795, 2022). "In the present study, KLK12 mRNA expression in tumor tissue of TNBC patients (n = 116) was determined by quantitative real-time PCR assay." (PMID 32028882, 2020). "Here, we quantified the KLK12 mRNA expression levels in tumor tissue of TNBC patients and analyzed their prognostic value." (PMID 32028882, 2020). "It has been well described that h-klk12 modulates many physiological processes, as well tumor cell invasion and metastasis." (PMID 24724053, 2014). "In particular, KLK12, which is responsible for tumor tumorigenesis, is highly expressed in CRC." (PMID 36703795, 2022). "The independent relationship of KLK12 mRNA levels with patient outcome was assessed in the complete cohort using multivariable Cox regression analysis, including the clinical variables age, lymph node status, tumor size, and histological grade (base model)." (PMID 32028882, 2020). "Thus, it is possible that tissue-specific factors influence and condition KLK12 gene expression in both healthy and tumor tissues." (PMID 32028882, 2020). "Positive, but low KLK12 mRNA levels were detected in 54 of 116 cases (47%), whereas the rest of the tumor tissues (n = 62, 53%) displayed negative KLK12 expression." (PMID 32028882, 2020). "As the tumor microenvironment may modulate the biological consequences of KLK actions, it may be desirable to study the KLK12 expression in a homogeneous cohort comprising only one cancer subtype." (PMID 32028882, 2020). "We will now describe in detail three notable genes from this category for which differential isoform usage may play a role in tumor development and growth: CDKN2A, FAM64A and KLK12." (PMID 25030904, 2014).
cancer (7 papers, 2004 to 2025). A tumor composed of atypical neoplastic, often pleomorphic cells that invade other tissues. "In both cases, the HR is around 2, indicating an about two-fold increased probability of disease progression and higher risk of cancer-related death in the KLK12 expressing group." (PMID 32028882, 2020). "Ample evidence substantiates that KLK12 mRNA levels are upregulated in cancer tissues, including gastric, breast, prostate, and colorectal cancer." (PMID 36293113, 2022). "Cytoband location 19q13.3–q13.4 was common for differentially expressed KLK gene family (KLK12, KLK11, KLK10, and KLK13), the serine proteases encoded from this Kallikrein gene family have been implicated in various cancers." (PMID 25505737, 2014). "Significant differences in expression levels were obtained for KLK12, especially when comparing the normal and cancer pools." (PMID 14710225, 2004). "Furthermore, KLK12 has been reported for its proangiogenic effect, thereby displaying a crucial role in the process of cancer." (PMID 32028882, 2020). "Basically, all KLKs are involved in cancer processes, whereby KLK12 mRNA transcripts were detected in many cancers, but not as protein." (PMID 41516101, 2025). "As KLK12 could activate proMMP-1 and -3, inhibition of KLK12 by TFPI-2 might limit MMP activation and inhibit cancer progression." (PMID 39153052, 2024). "Slightly higher expression levels were detected for KLK11 and KLK12 in normal breast compared to cancer, although not statistically conclusive." (PMID 14710225, 2004). "Importantly, cancer and LTBI were not ruled out in the healthy control subjects in our study and may account for the difference in the diagnostic accuracy between TB and bTB with KLK12." (PMID 36293113, 2022).
infection (5 papers, 2019 to 2022). The state of being infected such as from the introduction of a foreign agent such as serum, vaccine, antigenic substance or organism. "A significant reduction in the expression of MMP-1 and MMP-9 was observed in KLK12 knockdown RAW264.7 cells at 24h post-infection with M. bovis compared to control cells." (PMID 36293113, 2022). "We then examined the expression levels of KLK12 and MMP-1/-9 in RAW264.7 cells infected with NTMs and observed that MAP and M. smegmatis infection only upregulated MMP-1/-9 but downregulated KLK12." (PMID 36293113, 2022). "Using these two infection models, we confirmed that the transcription levels of KLK12, MMP-1, and MMP-9 in lung tissue were positively correlated with the initial dose of infection." (PMID 36293113, 2022). "After 3 and 12 weeks of infection the mice were sacrificed and qRT-PCR results showed a significant increased expression of KLK12 in the lungs and spleen of M. bovis infected mice as compared to the control group." (PMID 31060300, 2019). "KLK12 expression has been shown to be suppressed in CF cells compared to control cells 2 h post-infection with Pseudomonas aeruginosa." (PMID 31842871, 2019). "Knockdown of KLK12 increased the survival of M. bovis significantly in BMDMs after 24 h of infection while the difference in the survival rate of M. bovis at 6 h post infection was non-significant." (PMID 31060300, 2019). "Similarly, infection of both cell types with the M. bovis N strain also resulted in the upregulation of KLK12 in a dose- and time-dependent manner." (PMID 31060300, 2019). "Moreover, Western blot results also indicated the significant upregulation of KLK12 in BMDMs after infection with both M. bovis strains in a dose- and time-dependent manner." (PMID 31060300, 2019). "ELISA kits were used to detect serum levels of KLK12, MMP-1, and MMP-9 in mice with different infection doses, and the results were consistent with findings in lung tissues." (PMID 36293113, 2022). "Serum KLK12, MMP-1, and MMP-9 were significantly upregulated in mice after M. bovis infection, and the degree of upregulation was positively correlated with the initial infection dose." (PMID 36293113, 2022).
KLK12 also shares sentences with these, for which no sentence is quoted: Bovine Tuberculosis (1 paper); colon adenocarcinoma (1); colorectal tumor (1); lung squamous cell carcinoma (1); mesothelioma (1); thyroid carcinoma (1).